SLC26A3 (solute carrier family 26 member 3)
Description:
Mediates chloride-bicarbonate exchange with a chloride bicarbonate stoichiometry of 2:1 in the intestinal epithelia. Plays a role in the chloride and bicarbonate homeostasis during sperm epididymal maturation and capacitation (By similarity).
Synonyms: DRA; CLD
Tractability: Small molecule: a structure with a bound ligand is known. Antibody: UniProt places it where antibodies can reach, with high confidence; its Gene Ontology location is reachable by antibodies, with high confidence; UniProt predicts a signal peptide or a membrane-spanning region. PROTAC: ubiquitination databases record sites on it; a small molecule that binds it is known.
Target class: SLC26 family of anion exchangers; Electrochemical transporter; SLC superfamily of solute carriers; Transporter
Gene: Protein-coding gene on chromosome 7 (107,764,219 to 107,803,630, reverse strand). Ensembl gene ENSG00000091138.
Subcellular location: Apical cell membrane; Membrane; Cell membrane
Subcellular location (Human Protein Atlas): Acrosome
Pathways (Reactome):
Disease: Defective SLC26A3 causes congenital secretory chloride diarrhea 1 (DIAR1)
Transport of small molecules: Inorganic anion exchange by SLC26 transporters
Gene Ontology:
Molecular function: chloride:bicarbonate antiporter activity; protein binding; bicarbonate transmembrane transporter activity; chloride transmembrane transporter activity; oxalate transmembrane transporter activity; solute:inorganic anion antiporter activity; sulfate transmembrane transporter activity; secondary active sulfate transmembrane transporter activity
Biological process: cellular response to cAMP; chloride transmembrane transport; intracellular pH elevation; membrane hyperpolarization; monoatomic anion transport; sperm capacitation; sulfate transmembrane transport; transmembrane transport; bicarbonate transport; oxalate transport
Cellular component: apical plasma membrane; plasma membrane; membrane; sperm midpiece; brush border membrane
Genetic constraint (gnomAD): Loss-of-function variants: 50 observed, 73.82 expected, observed/expected ratio (o/e) 0.68, 90% interval 0.54 to 0.86. The upper end of that interval is the gene's LOEUF score, 0.86, which puts it in group 3 of 6, group 1 being the genes least tolerant of losing a copy. Missense variants: 814 observed, 868.29 expected, observed/expected ratio (o/e) 0.94, 90% interval 0.88 to 0.99. Synonymous variants: 312 observed, 318.42 expected, observed/expected ratio (o/e) 0.98, 90% interval 0.89 to 1.08.
Homologues: Orthologues: chimpanzee SLC26A3 (98% identical), macaque SLC26A3 (88% identical), pig SLC26A3 (82% identical), rat Slc26a3 (81% identical), mouse Slc26a3 (81% identical), dog SLC26A3 (80% identical), guinea pig SLC26A3 (78% identical), rabbit SLC26A3 (78% identical), tropical clawed frog slc26a3 (65% identical), tropical clawed frog slc26a3.2 (58% identical), zebrafish slc26a3.2 (55% identical), zebrafish slc26a3.1 (53% identical). Paralogues in human: SLC26A4 (46% identical), SLC26A5 (36% identical), SLC26A6 (35% identical), SLC26A9 (33% identical), SLC26A2 (29% identical), SLC26A8 (29% identical), SLC26A7 (28% identical), SLC26A1 (27% identical), SLC26A11 (21% identical).
Diseases named in the same sentence as SLC26A3 in open-access papers:
SLC26A3 is named in the same sentence as 75 diseases in open-access papers, as found by Europe PMC text mining. Sharing a sentence is not in itself a finding about the gene and the disease. The quoted sentences say what the papers report.
adenoma (37 papers, 2009 to 2026). A neoplasm arising from the epithelium. "Slc26a3 encodes for the Downregulated in Adenoma (DRA), a Cl−/HCO3− exchanger, which mediates the apical chloride absorption into the ECs and the secretion of bicarbonate into the lumen." (PMID 35458125, 2022). "Genetic analyses have shown that mutations in human SLC26A3 (also known as DRA; downregulated in adenoma) result in CCD." (PMID 33514305, 2021). "This is facilitated by the coupled activity of the Na+/H+ exchanger NHE3 (sodium: proton exchanger-3 encoded by the SLC9A3 gene) and the Cl−/HCO3− exchanger DRA (Downregulated in Adenoma encoded by the SLC26A3 gene), with DRA predominantly expressed in the distal colon." (PMID 41009702, 2025). "In the colon, specifically, SLC26A3 (also known as DRA [downregulated in adenoma]) plays a critical role in anion transport and fluid absorption." (PMID 41359652, 2025). "Linaclotide-stimulated bicarbonate secretion was eliminated by down-regulated in adenoma (DRA, SLC26A3) inhibition during loss of CFTR activity." (PMID 37205513, 2024). "SLC26A3, also known as the downregulated in adenoma (DRA) protein or chloride/bicarbonate exchanger, is primarily responsible for the absorption of oxalate in the intestine." (PMID 37371749, 2023). "The Cl−/HCO3− exchanger (SLC26A3), also known as DRA (downregulated in adenoma), cooperates with NHE3 in order to achieve salt absorption by electroneutral ion transport across the apical membrane." (PMID 35665228, 2022). "So far, two apical chloride/bicarbonate (Cl−/HCO3−) exchangers PAT1 (putative anion transporter 1, Slc26a6) and DRA (downregulated in adenoma, Slc26a3) have been shown to be involved in the secretion and absorption of oxalate, respectively." (PMID 33904662, 2021). "One functional group of transporters to be discussed are Cl−/HCO3− exchangers belonging to the class of SLC (solute carrier) 4 proteins such as AE1 (SLC4A1), AE2 (SLC4A2), and AE3 (SLC4A3), or SLC26 proteins such as DRA (SLC26A3; downregulated in adenoma)." (PMID 33914143, 2021). "SLC26A3, previously known as downregulated in adenoma (DRA), is located on chromosome 7q31 and consists of 21 exons." (PMID 32951339, 2020). "The downregulation of a DRA gene (SLC26A3) is observed in adenomas and adenocarcinomas of the colon." (PMID 31947992, 2020). "Coupled NaCl absorption occurs via the dual operation of Na:H (NHE3; Slc9a3) and Cl:HCO3 (Down Regulated in Adenoma (DRA; Slc26a3) or Putative Anion Transporter 1 (PAT1; Slc26a6)) exchange." (PMID 30126234, 2018). "The gene with highest discriminatory power was the SLC26A3, synonymous to downregulated in adenoma (DRA) that was overexpressed in the metastatic AD." (PMID 25325012, 2014). "The extensive body of evidence on the regulation and roles of SLC26A3 in cancer is discussed in the section Down-Regulated in Adenoma (SLC26A3, DRA)." (PMID 24795638, 2014). "One in particular has received widespread attention for its dysregulation in CRC, namely SLC26A3, also known as Downregulated in Adenoma (DRA), which was first described as a gene downregulated in CRC in 1993." (PMID 24795638, 2014). "Among the most down-regulated genes, we found Slc26a3 (solute carrier family 26, member 3, also known as down-regulated in adenoma (Dra)), Mptx (mucosal pentraxin), Retnla (resistin like-α), Muc2 (mucin 2)." (PMID 20459814, 2010). "The few studies investigating expression of SLC26A3 so far have only used subtractive hybridization and northern blot to show that SLC26A3 is downregulated in adenomas of colon." (PMID 19678923, 2009). "Coupled NaCl absorption occurs via the functional coupling of villus cell brush border membrane (BBM) Na:H exchange (NHE3, sodium–hydrogen exchanger 3/SLC9A3) and Cl:HCO3 exchange (DRA, downregulated in adenoma/SLC26A3 and PAT1, putative anion transporter-1/SLC26A6)." (PMID 39456989, 2024).
adenoma (continued). "The 21-exon solute carrier family 26 member 3 (SLC26A3) gene is mapped to chromosome 7q31 and encodes for the chloride/bicarbonate exchanger, also known as down regulated in adenoma (DRA), a transmembrane protein localized mainly to the apical side of the mucosa in the ileum and proximal colon." (PMID 36422736, 2023). "In addition to PAT1, the other major apical Cl−/HCO3− exchanger in the intestine is SLC26A3 (down-regulated in adenoma, or DRA)." (PMID 36901725, 2023). "This hypothesis is consistent with earlier reports that the expression of the anion-exchanger SLC26A3 (Down-Regulated in Adenoma, DRA) decreases during colon carcinogenesis." (PMID 30834261, 2019). "Thus, consistent with published findings [see section Down-Regulated in Adenoma (SLC26A3, DRA)], SLC26A3 is down-regulated in colon cancer, but furthermore, our analyses reveal that this gene is also widely down-regulated in breast cancer." (PMID 24795638, 2014). "Glucose-independent salt absorption in the small intestine is mediated via the chloride/base exchangers, down-regulated in adenoma (DRA; SLC26A3) and putative anion transporter 1 (PAT1; SLC26A6), working in parallel with the Na+/H+ exchanger 3 (NHE3)." (PMID 36901725, 2023). "SLC26A3 (DRA, downregulated in adenoma) is an anion exchanger of chloride, bicarbonate, and oxalate thought to facilitate intestinal oxalate absorption, as evidenced by approximately 70% reduced urine oxalate excretion in knockout mice." (PMID 35608921, 2022). "This is achieved via CFTR and apical Cl-/HCO3- exchangers: downregulated in adenoma (DRA, Slc26a3), putative anion transporter 1 (PAT-1, Slc26a6), and anion exchanger isoform 4 (AE4, Slc4a9)." (PMID 36006975, 2022). "In the mammalian intestine, the two key BBM Cl−/HCO3− exchanger proteins of the SLC26 family, Down-Regulated in Adenoma (DRA, SLC26A3) and putative anion transporter-1 (PAT1, SLC26A6), mediate Cl− absorption." (PMID 33920650, 2021). "SLC26A3, or DRA (downregulated in adenoma), is a transporter expressed in mammals, including rodents and humans, that exchanges chloride for bicarbonate." (PMID 30837228, 2019). "Two members of the family, SLC26A3 (DRA; downregulated in adenoma) and SLC26A6 (PAT1; putative anion transporter-1), were reported to be expressed in the luminal membrane of pancreatic ducts and function as Cl−–HCO3− exchangers." (PMID 29399744, 2018).
inflammatory bowel disease (11 papers, 2019 to 2025). A spectrum of small and large bowel inflammatory diseases of unknown etiology. "Both patients with CLD and slc26a3-deficient mice have an elevated risk of inflammatory bowel disease (IBD)." (PMID 39992989, 2025). "SLC26A3 encodes a key intestinal chloride anion exchanger and is a susceptibility gene for inflammatory bowel disease." (PMID 39300663, 2024). "Furthermore, the downregulation of LINC01564 has been associated with genomic instability and metabolic adaptation in liver cancer, while SLC26A3 has been linked to inflammatory bowel disease and infectious diarrhea." (PMID 38808330, 2024). "The mutation of SLC26A3 was associated with inflammatory bowel disease (IBD)." (PMID 34783577, 2021). "Currently, research on SLC26A3 primarily focuses on its significant role in congenital chloride diarrhea and inflammatory bowel disease." (PMID 37573425, 2023). "A number of reports suggest that biallelic mutations in SLC26A3 may confer increased risk for the development inflammatory bowel disease (IBD) later in life." (PMID 36422736, 2023). "Subjects with congenital chloride diarrhea (CLD; a defect in solute carrier family 26 member 3 (SLC26A3)) are prone to inflammatory bowel disease (IBD)." (PMID 35679312, 2022). "SLC26A3 expression is decreased in inflammatory bowel disease." (PMID 40003915, 2025). "Furthermore, patients with diarrhea associated with inflammatory bowel disease (IBD), either ulcerative colitis (UC) or Crohn’s disease (CD), exhibit reduced SLC26A3 expression." (PMID 31114672, 2019). "The autosomal recessive disease congenital chloride diarrhea (CLD), caused by loss-of-function mutations in the solute carrier family 26 member 3 (SLC26A3) gene, shows association with inflammatory bowel disease (IBD)." (PMID 39992989, 2025). "The risk for inflammatory bowel disease (IBD) is elevated both in human CLD and in slc26a3-deficient mice." (PMID 35679312, 2022). "SLC26A3 is a key chloride-bicarbonate exchanger protein contributed to infectious diarrhea and inflammatory bowel disease (IBD)." (PMID 35433778, 2022).
colorectal cancer (10 papers, 2009 to 2026). A primary or metastatic malignant neoplasm that affects the colon or rectum. "Despite significant research findings, little is known about the function of SLC26A3 in human colorectal cancer." (PMID 37573425, 2023). "Transient transfection of Flag-SLC26A3-STAS domain plasmid resulted in reduced malignant biological behaviors in colorectal cancer cells." (PMID 37573425, 2023). "Despite its clinical relevance, the molecular mechanism of SLC26A3 in regulating the malignant biological behaviors of colorectal cancer cells remains largely unknown." (PMID 37573425, 2023). "Hence, to elucidate the molecular mechanism of SLC26A3 in CRC progression, we overexpressed the SLC26A3 gene in colorectal cancer cell lines and performed RNA sequencing on cells with SLC26A3 overexpression." (PMID 37573425, 2023). "We showed that SLC26A3 promoted NHERF2 interaction with IκB in colorectal cancer cells." (PMID 37573425, 2023). "Therefore, further studies are necessary to investigate the effect of SLC26A3 on the progression of colorectal cancer." (PMID 37573425, 2023). "The down expression of five genes (SLC26A3, GUCA2A, CLCA4, CLCA1, and AQP8) was significantly associated with poor overall survival in colorectal cancer adenocarcinoma patients, and patients with lower expression levels of CLCA1 had poorer disease-free survival rates." (PMID 35693937, 2022). "The expression of solute carrier family 26 member 3 (SLC26A3) is closely related to the occurrence and development of colorectal cancer (CRC), but the specific molecular mechanisms remain unclear." (PMID 41617682, 2026). "Additionally, SLC26A3, particularly its STAS domain, has been demonstrated to inhibit proliferation in colorectal cancer cells, indicating a growth regulatory role." (PMID 37573425, 2023).
colitis (9 papers, 2008 to 2025). Inflammation of the colon. "This is supported by mouse studies of Slc26a3 deficiency that show increased susceptibility to induction of colitis and consistent with data that show DRA expression is diminished in intestinal inflammatory states." (PMID 36422736, 2023). "Intestinal SLC26A3 mRNA has been reported to be downregulated in ulcerative colitis and in the IL10 transgenic colitis model, but SLC26A3 protein levels in intestinal tissues of patients with ulcerative colitis were unchanged." (PMID 26157392, 2015). "Finally, SLC26A3, also differentially expressed in directionally concordant analyses, is expressed at high levels in the classical NEC epithelium, as it is in human CD and animal models of colitis, and low levels in the cardiac NEC epithelium." (PMID 40201118, 2025).
colon carcinoma (9 papers, 2008 to 2025). "Polymorphic variants of SLC26A3 have also been linked to prognosis of patients with colon carcinoma and to neoadjuvant therapy resistance in HER2-negative breast carcinoma." (PMID 26157392, 2015). "In this relation, in a few numbers of studies it has been proposed that SLC26A3 primarily expressed in colon cancer, but its expression level is significantly decreased in CRC, indicating its association with the progression of CRC." (PMID 35907803, 2022). "SLC26A3 was originally thought to be a transcription factor and a potential colon tumour suppressor based on protein libraries from normal colon and colon cancer cells." (PMID 32662230, 2020). "CLD patients are at increased risks of IBD and colon cancer, indicating a new clinical role of SLC26A3 as a key molecule in colonic mucosal defence." (PMID 32662230, 2020). "SLC26A3 was shown to be primarily expressed in colon cancer, but its expression is significantly decreased in colon cancer and colon cancer cell lines, and the down‐regulated expression of SLC26A3 was shown to be associated with the progression of colon cancer." (PMID 32662230, 2020). "SLC26A3 downregulation correlates with colon tumor progression; and in congruence with this, expression levels for SLC26A3 have been reported to be controlled by miR-31, which is upregulated in tumors from patients with progressive CRC compared to patients with disease control." (PMID 24795638, 2014). "It is not clear at this point, however, whether the correlation between SLC26A3 and colon cancer is due to its role in HCO−3 transport (and hence to regulation of pHi and local pHe), a role in cellular Cl− homeostasis, or other less understood functions." (PMID 24795638, 2014). "Notably, a number of genes profoundly downregulated in susceptible FVB mice, such as Slc26a3 (Dra), Aqp8, CAIV, and Slc5a8 (Ait), are also implicated in the development of colonic tumors." (PMID 18680595, 2008). "SLC26A3/DRA is an anion transporter expressed predominantly in the mucosa of the lower gastrointestinal tract and is downregulated in polyps, colon tumors, and inflammatory bowel disease." (PMID 39948151, 2025).
Congenital chloride diarrhea (9 papers, 2018 to 2025). "SLC26A3: Mutations in SLC26A3 have been shown to be associated with congenital chloride diarrhea (CLD), a genetic disorder consisting of hypochloremia, alkalosis, and diarrhea, with V317del being the most common variant in the Finnish population." (PMID 35409285, 2022). "Congenital chloride diarrhea (CCD) is caused by a recessive mutation in the SLC26A3 gene and characterized mainly by watery diarrhea, hypochloremia and metabolic alkalosis." (PMID 34988036, 2021). "SLC26A3, also known as DRA (Congenital Chloride Diarrhea), encodes a protein typically expressed in enterocytes that contributes to the chloride reabsorption." (PMID 30161141, 2018). "A rare autosomal recessive disease congenital chloride diarrhea (CLD; OMIM #214700) is caused by mutations in the solute carrier family 26 member 3 (SLC26A3 alias DRA) gene on chromosome 7q22.3–31.1." (PMID 35679312, 2022). "Congenital chloride diarrhea (CLD; OMIM 214700) is a rare autosomal recessive disorder caused by pathogenic variations in the solute carrier family 26 member A3 (SLC26A3) gene." (PMID 32295532, 2020). "Objectives and Study: Congenital chloride diarrhea (CCD) is a rare, autosomal recessive disorder caused by mutations in the SLC26A3 gene encoding a transmembrane chloride/bicarbonate ion exchanger mainly expressed in the apical brush border of the ileal and colonic epithelium." (PMID 32850522, 2020).
ulcerative colitis (6 papers, 2012 to 2025). An inflammatory bowel disease involving the mucosal surface of the large intestine and rectum. "In a clinical study on Chinese population, SLC26A3 polymorphism was a risk factor for the development of ulcerative colitis." (PMID 36451813, 2022). "Polymorphisms in the SLC26A3 gene have been linked to ulcerative colitis in Japanese and Korean patients, but not to Crohn's disease." (PMID 26157392, 2015). "SLC26A3 expression is notably decreased in animal models of infectious colitis and inflammation-associated diarrhea, with genome-wide association studies in Japanese populations indicating that SLC26A3 deficiency is associated with an increased risk of developing ulcerative colitis." (PMID 40585902, 2025). "Several studies have linked SLC26A3 polymorphisms or downregulation to ulcerative colitis (UC), and low or absent SLC26A3 expression to intestinal adenomas and adenocarcinomas." (PMID 35679312, 2022).